CRP (C-reactive protein)
Diseases named in the same sentence as CRP in open-access papers (continued):
Sharing a sentence is not in itself a finding about the gene and the disease.
anemia (continued). "Laboratory investigations are non-specific, but high levels of white blood cell count and C-reactive protein, anemia, and high erythrocyte sedimentation rates provide clinical clues of associated infection." (PMID 31653245, 2019). "Laboratory data are nonspecific, including results regarding anemia, leukocytosis, increased erythrocyte sedimentation rate, raised high-sensitivity C-reactive protein, and elevated alkaline phosphatase in hepatic actinomycosis." (PMID 31804331, 2019). "A blood test revealed anemia (hemoglobin 8.6 g/dL) with a slight elevation of CRP level (1.25 mg/dL), and the FOBT was negative." (PMID 32039112, 2019). "While the levels of ESR, CRP, and WBC vary in TB, there may also be signs of chronic inflammation such as anemia, hypoalbuminemia, and thrombocytosis." (PMID 31375006, 2019). "Specifically, to screen for anemia in IBD patients TfS <20% and a serum ferritin concentration <30 g/L (with a serum CRP level within the normal range or a ferritin concentration of less than 100 g/L with an elevated serum CRP level) are specified." (PMID 31614529, 2019). "The laboratory examination revealed an elevated C-reactive protein (CRP) level without anemia and microscopic hematuria and pyuria." (PMID 31123939, 2019). "Age, the percentage of women, education level, and the level of sensitivity C-reactive protein among participants with anemia were higher than those without anemia." (PMID 29507334, 2018). "Laboratory tests may show evidence of malabsorption, eosinophilia, erythrocyte sedimentation rate (ESR) and C-reactive protein (CRP) elevation, anaemia, thrombocytosis, and lymphopenia." (PMID 30020975, 2018). "Subjects who had anemia had a more positive response to C-reactive protein 52.2% (48/92) than the non-anemic pregnant women 28.8% (19/66)." (PMID 30237895, 2018). "The issue is more complex for men, but it is striking that over half the men aged 80 years or over who did not have comorbid disease or elevated CRP fulfilled the current definition for anaemia." (PMID 29680801, 2018). "In the setting of RA, RDW has been found to be higher when compared to osteoarthritis, and RDW was positively correlated with CRP regardless of anemia." (PMID 30363719, 2018). "We also found that the level of sensitivity C-reactive protein in participants with anemia was higher than those without anemia." (PMID 29507334, 2018). "Age, gender, anemia, T stage, grade, and CRP level elevation were not significant predictors in the univariate analysis." (PMID 28469275, 2017). "Elevated sST2 correlated with male gender, history of prior-transplants, CVE, positive stress test, LVH, elevated cTnT, anemia, hyperphosphatemia, increased CRP and non-transplanted status." (PMID 28704488, 2017). "Basic laboratory follow-up must include CBC (with special attention to anemia, leukocytosis with increased neutrophil count, and thrombocytosis), ESR, CRP, serum liver enzymes, muscle enzymes, and metabolic profile (including glucose, triglyceride, and cholesterol levels)." (PMID 28848544, 2017). "A blood test was performed showing only lymphopenia (600 x 106/L) without anaemia or elevated C-reactive protein (CRP)." (PMID 28358876, 2017). "There were 267 patients (45.3%) with anemia, 146 (24.7%) with abnormal white blood cells, 117(19.8%) with thrombocytopenia, 382 (64.7%) with elevated erythrocyte sedimentation rate (ESR) and 261 (44.2%) with increased C-reactive protein (CRP)." (PMID 28459811, 2017). "Some that are already broadly adopted are elevated C-reactive protein (CRP), elevated erythrocyte sedimentation rate (ESR), low albumin, anemia, elevation of alanine aminotransferase (ALT), a high platelet count after 7 days, and a high white blood cell count or pyuria." (PMID 29358841, 2017). "Physicians should perform fibreoptic bronchoscopy in MPA patients with lung abnormalities and unidentified anaemia as soon as they can, even if the patients have no respiratory symptoms or elevation of CRP." (PMID 28050304, 2016).
anemia (continued). "Among men with anemia, there was a correlation with increased CRP, but not with increased ferritin (>275 μg/L) or transthyretin (<0.23 g/L)." (PMID 27912734, 2016). "The two groups were not significantly different with respect to their anaemia and CRP status at baseline." (PMID 26955479, 2016). "The hemoglobin was comparable between the patients with unexplainable and explainable anemias, and both groups had significantly increased CRP, as compared to patients without anemia." (PMID 27221100, 2016). "The percentage of patients with elevated CRP levels was not significantly different between two groups, but the rate of anemia in the thrombocytosis group was higher (P = 0.030)." (PMID 26965460, 2016). "It was significantly associated with age older than 50 years, metabolic syndrome, C-reactive protein levels, effective blood flow ≤ 300 mL/min, severe anemia, and absence of mild anemia." (PMID 26294974, 2015). "Features suggestive of chronic disease and inflammation (anaemia, elevated ESR/CRP) are also seen." (PMID 26558124, 2015). "We did not measure more accurate markers of inflammation, but several studies have clearly demonstrated that CRP levels positively correlate with the severity of anemia and EPO resistance in CKD patients, and that CRP concentrations closely reflect Interleukin-6 levels." (PMID 25781618, 2015). "The patients’ CRP, ESR and Hgb before and after anemia approaches*." (PMID 25901156, 2015). "Of these women, 4.8% had anemia (hemoglobin<11 g/dL) and 2.4% had elevated CRP concentration (CRP>3 mg/L) and hence were not included in the study." (PMID 25660254, 2015). "Firstly: the key determinants of Zn status, including: hair zinc levels, iron or hemoglobin status for anemia, presence of acute illness, inflammation markers, including C Reactive Protein and serum Albumin were not estimated in this study." (PMID 24401366, 2014). "In this study, high NT-proBNP, hypoalbuminemia, anemia, and high c-TnT all showed a significant correlation with mortality whereas elevated CRP did not." (PMID 26557244, 2014). "On the other hand, testosterone treatment of castrated animals seems to cause anaemia and weaker bactericidal capacity when compared to non-castrated and testosterone-treated rats, but better WBC and CRP results when compared to the castrated, untreated group." (PMID 25001579, 2014). "Instead, patients with anemia had a lower DAS28 (P = 0.005) and lower CRP levels (P = 0.015)." (PMID 24804270, 2014). "The high-CRP group was characterized by a higher proportion of patients with age >60 years, more frequent B symptoms, elevated LDH levels, elevated KPI scores, hypoalbuminemia, and anemia." (PMID 23724031, 2013). "Laboratory findings did not reveal anemia (haemoglobinemia = 13 g/dl) or inflammatory changes (sedimentation rate = 8mm, leucocytes 9600/mm3, C. Reactive Protein (CRP) = 0.8 mg/dl)." (PMID 24570788, 2013). "However, when these factors were enrolled in multivariate analysis, only CRP, EBVDNA, and anemia were independent factors." (PMID 24130817, 2013). "Although the dog showed no specific clinical signs, thrombocytopenia, anaemia and elevated C-reactive protein (CRP) were observed." (PMID 22401583, 2012). "In this study, anaemia was present in the majority of patients, irrespective of their C-reactive protein levels." (PMID 21547258, 2011). "Routine blood test results were normal except elevated creatinine (192 μmol/L; normal range 63–107), urea (11.8 mmol/L; normal range 2.8–8.3) and C-reactive protein (CRP) (105 mg/L; normal range < 5) levels and mild anemia (hemoglobin 109 g/L; normal range 138–175)." (PMID 22933926, 2010). "Blood tests demonstrated normal white cell count (9500/μl), anemia (hematocrit 32,6% and hemoglobin 10,7 gr/dl), mild thrombocytosis (512000/μl), increased erythrocyte sedimentation rate (ESR = 109 mm/hr) and C-reactive protein (CRP = 49,6 mg/dl)." (PMID 20062600, 2009).
anemia (continued). "Laboratory abnormalities may include anemia, leukocytosis, increased erythrocyte sedimentation rate (ESR), elevated C-reactive protein (CRP), and hypergammaglobulinemia." (PMID 18652657, 2008). "Anemia was defined as hemoglobin < 13 mg/dl in males and < 12 mg/dl in females and further categorized into nutritional and non-nutritional anemia based on several nutritional (ferritin, Vitamin B12, and folate), inflammatory (ferritin, C-reactive protein), and renal (serum creatinine) biomarkers." (PMID 41239451, 2025). "Laboratory tests may reveal nonspecific results such as mild anemia with a normal white blood cell count, and elevated acute phase reactants, such as C-reactive protein and erythrocyte sedimentation rate." (PMID 41244976, 2025). "Potential blood markers for IVLBCL include elevated levels of CRP, ferritin, fibrinogen, LDH, and β2-microglobulin, as well as cytopenia affecting at least one cell line, which may manifest as anemia, lymphopenia, or thrombopenia, which have been noted in most cases." (PMID 40423224, 2025). "Evaluating anemia following sufficient rest is advisable, yet not always possible, and clearly, adding measurement of serum iron and/or inflammatory markers (hs-CRP, hepcidin) to the usually measured ferritin in the cases of anemia workup may be needed." (PMID 41470772, 2025). "Notably, anemia improvement is observed in patients with high CRP levels at the same dose as in the non-inflammatory state." (PMID 41573727, 2025). "The laboratory results showed anemia and an elevated C-reactive protein, but no hormone production." (PMID 38783354, 2024). "As the responsiveness to vadadustat did not decrease in inflammatory conditions with high CRP levels at baseline, vadadustat may be a better option for treating anemia in patients with inflammation." (PMID 38530490, 2024). "Laboratory tests performed on admission showed the presence of anemia (RBC 3.54 * 10^12/L, HGB 87 g/L, HCT 0.28 with a mildly elevated white blood cell count of 9.98 *10^9/L (normal value < 9.5 *10^9/L) and a mildly elevated C-reactive protein level of 13.6 mg/L (normal value < 3 mg/L)." (PMID 38418948, 2024). "A lack of resolution in anemia (Hgb HR 3.10; Hct HR 2.53; p < 0.001), hypercalcemia (HR 3.98, p < 0.001), elevated CRP (HR 2.11, p < 0.001), elevated ESR (HR 3.01, p < 0.001), elevated LFTs (HR 1.92, p = 0.014), and elevated NLR (HR 1.80, p = 0.016) were associated with significantly worse OS." (PMID 39518116, 2024). "In addition, laboratory variables that could guide us towards NI forms are represented by unexplained anemia, high PLT count during hospitalization, high CRP and ferritin, and hyponatremia at the time of admission." (PMID 38790534, 2024). "Significantly worse CSS was observed in patients with a lack of resolution in anemia (Hgb HR 3.34; Hct HR 3.14; p < 0.001), hypercalcemia (HR 5.16, p < 0.001), elevated CRP (HR 2.58, p < 0.001), elevated ESR (HR 3.31, p < 0.001), and elevated LFTs (HR 2.12, p = 0.018)." (PMID 39518116, 2024). "Over the next two years, the patient was treated with prednisone and various immunosuppressive drugs, but while the white blood cell count and platelet count remained stable, the anemia worsened progressively, CRP increased progressively, and IgG4 did not decrease significantly." (PMID 37784011, 2023). "However, in our study, after carefully controlling for the various relevant confounders, we provide evidence that serum CRP and hemoglobin levels, which are markers of systemic inflammation and anemia, respectively, were not affected by the severity of OSA." (PMID 36980461, 2023). "All patients presented high C-reactive protein concentrations, anemia and negative blood cultures." (PMID 37676863, 2023).
anemia (continued). "Furthermore, group II patients also had significantly heightened pathological conditions than group I, including anemia, ESR, CRP, and different parameters of LN, including (24 h urinary protein, active urinary sediment including casts, hematuria, pyuria, albuminuria, BUN, and serum creatinine)." (PMID 36205758, 2023). "Laboratory testing that may be pertinent during the initial evaluation of anemia in EB patient should include CBC, reticulocyte count, ferritin, CRP levels and TIBC; in patients with severe generalized forms of EB, screening should be done at diagnosis and repeated every 6 months." (PMID 36823529, 2023). "Severe regenerative anemia (hematocrit 15.3%, negative saline agglutination test, negative slide agglutination test, negative Coomb's test, prominent spherocytes) elevated liver enzymes, and increased CRP and D-dimer were observed in blood tests." (PMID 36118327, 2022). "Furthermore, we were able to select a large patient cohort only consisting of patients with clinical (HBI or SCCAI scores) and biochemical (CRP) remission in the absence of anemia." (PMID 36028644, 2022). "Laboratory analysis revealed microcytic normochromic anaemia with a haemoglobin level of 10.7 g/dL, neutrophilic leucocytosis of 15,500/μL, an erythrocyte sedimentation rate (ESR) of 78 mm/h, and a C-reactive protein (CRP) level 5 times the upper limit of normal (ULN)." (PMID 36128217, 2022). "In future studies, the cut-off values, at which hepcidin, IL-6, and CRP concentrations may differentiate future anaemia patients from patients who are not expected to develop anaemia, must be determined." (PMID 36612220, 2022). "An initial CBC at our hospital disclosed a regenerative anemia (PCV, 26%; reference: 37%–55%), increased alanine aminotransferase (ALT) (179 U/L; reference: 17–78 U/L), alkaline phosphatase (ALP) (624 U/L; reference: <254 U/L), and C-reactive protein (CRP) (2.75 mg/dl; reference: <1.0 mg/dl)." (PMID 35898238, 2022). "If overall inflammation was dampened, this might explain why CRP did not directly influence anemia or sTfR and why it occupied lower rank in dominance for serum iron and ferritin." (PMID 36079755, 2022). "Moreover, we discovered statistically significant differences in CRP concentrations, with non-anaemia women having significantly higher CRP levels (me = 29.74 mg/L) than women who developed anaemia post-operatively (me = 1.85 mg/L, p = 0.040306)." (PMID 36612220, 2022). "Moreover, chronic obstructive pulmonary disease (COPD) patients with anemia had significantly higher CRP levels compared with the control subjects or those without anemia (both p < 0.001)." (PMID 33810272, 2021). "Moreover, age, male sex, use of non-calcium-based phosphate binders, and CRP levels were significantly related with the development of anemia." (PMID 34931015, 2021). "When considering anemia only (no alterations in CRP levels), the prevalence was 8.8%." (PMID 34830693, 2021). "Laboratory testing of patients with brucellosis may show anemia, leukopenia, and pancytopenia, secondary to bone involvement, as well as elevated inflammatory markers such as erythrocyte sedimentation rate (ESR) and C-reactive protein (CRP)." (PMID 33274162, 2020). "Multiple regression analysis using models 1 and 2 showed that the prevalence of anemia gradually increased in accordance with the progression of G category in each set of criteria, independent of age, A category, albumin level, CRP, and sex (notably, sex was only included for JSDT2 Criteria)." (PMID 32687544, 2020). "There were 4 significant high score-by-subgroup interactions for infection during hospitalization: patients less than 80 years old, those without anemia, and those without renal dysfunction, and those with CRP levels> 1 mg/dL showed directionally worse impact of the high CONUT score." (PMID 32094392, 2020).
anemia (continued). "As expected, patients with AI had the highest CRP (8.69 mg/dL, p < 0.001) and IL-6 levels (82.7 ng/L, p = 0.007) when compared to patients with IDA (0.12 mg/dL, 3.4 ng/L, respectively) or unclassified/multifactorial anemia (7.79 mg/dL, 70.3 ng/L, respectively)." (PMID 32751400, 2020). "Laboratory tests revealed anemia (hemoglobin 10.2 g/dL, hematocrit 32.2%, and mean corpuscular volume 81 fl), a normal white cell and platelet count, and both an elevated erythrocyte sedimentation rate (ESR) (135 mm/h) and an elevated C-reactive protein (CRP) level (12 mg/dL, normal 0-1)." (PMID 27579040, 2016). "The most common clinical signs and laboratory abnormalities of febrile dogs diagnosed with Rickettsia infection based on seroconversion and/or PCR were fever, lethargy, myalgia, lameness, elevation of C-reactive protein, hypoalbuminemia, thrombocytopenia and mild non-regenerative anemia." (PMID 25886403, 2015). "By 6 months of age, CRP concentrations remained elevated in anemic compared to non-anemic infants and 12% infants fulfilled criteria for anemia of inflammation; however, plasma hepcidin levels were more modestly elevated in anemic infants at 6 months, compared to infants at 3 months." (PMID 26252205, 2015). "This study showed that arginine is beneficial as supplement treatment in patients with active tuberculosis, an effect most likely improved constitutional symptoms, weight gain, and reduction of CRP despite the lack of effect on anemia, cough, sputum smear conversion, and final treatment success." (PMID 25734013, 2015). "Interestingly, GlycA appears to be influenced less by non-inflammatory conditions such as age, anemia, and BMI than by CRP or ESR." (PMID 25956924, 2015). "A deficiency in the modified Duke criteria becomes apparent when diagnosing IE when blood cultures are negative; we have shown that these patients often have elevated sedimentation rates and C-reactive protein levels from repeated non-cardiac infection and anaemia." (PMID 24844548, 2014). "There are no blood or effluent markers specific to the diagnosis of EPS, elevated levels of C-reactive protein, anemia, hypoalbuminemia may be found but are nonspecific." (PMID 25870687, 2014). "Our findings suggest that patients with stage IV CRC with low ploidy score and CRP levels, absent or mild anaemia, and normal albumin levels might derive greatest benefit from palliative chemotherapy." (PMID 23840958, 2013). "Episodes of fever, nonproductive cough, left thoracic pain, vein thrombosis, hypochromic anemia, reduced numbers of leukocytes, decreased percentage of lymphocytes, increased proportion of monocytes and elevated levels of CRP, microbiological analysis were negative." (PMID 22515314, 2012). "After supplementation, the prevalence of elevated FGF23 was 16% (P=0.1), the prevalence of anaemia had decreased to 62% (P=0.0005), there were no subjects with low Ferr (P≤0.0001) and the frequency of subjects with CRP ≥ 5 mg/dL did not significantly change (P=1.0)." (PMID 23098062, 2012). "One hundred children with anemia were taken as the study group and another 100, age - and sex-matched children without anemia were taken as the control.They were subjected to complete blood count (CBC) C-reactive protein (CRP) estimation, Mantoux test and chest X-ray." (PMID 20616934, 2010). "Considering the dynamic balance and negative feedback mechanism of the body, whether CRP and the inflammatory state represented by CRP will further aggravate the decrease in serum iron levels, thus affecting anemia, has no research to support at present and is worth further discussion." (PMID 38562035, 2024). "Systemic inflammation specified by elevated CRP levels may reflect a direct effect of inflammation leading to an immunosuppressive TME or merely indicating an advanced cancer with systemic manifestation such as anorexia, cachexia, and anemia resulting immunosuppression." (PMID 37329173, 2023).